GAPDH (glyceraldehyde-3-phosphate dehydrogenase)
Diseases named in the same sentence as GAPDH in open-access papers (continued):
Sharing a sentence is not in itself a finding about the gene and the disease.
colorectal cancer (41 papers, 2012 to 2025). A primary or metastatic malignant neoplasm that affects the colon or rectum. "Recently, it has been demonstrated that VC at pharmacological plasma concentrations, acquired intravenously, can selectively kill KRAS- or BRAF-mutated colorectal cancer cells by targeting GAPDH." (PMID 36787291, 2023). "According to a recent study, VC can selectively kill KRAS/BRAF-mutated colorectal cancer cells by targeting GAPDH." (PMID 36787291, 2023). "A recent study demonstrates the toxicity of a lipopeptidyl benzophene, asperphenin B, on human colorectal cancer cells associated with the downregulation of GAPDH expression." (PMID 34880756, 2021). "A study on vitamin C on human colorectal cancer cells suggests that ROS are implicated in the mechanism by which vitamin C inhibits GAPDH." (PMID 34880756, 2021). "Indeed, an increased expression of GAPDH in human colorectal cancer cells was associated with epithelial to mesenchymal transition (EMT) accompanied by the upregulation of mesenchymal markers." (PMID 34880756, 2021). "Metabolomics revealed that vitamin C causes pentose phosphate pathway metabolites and glycolytic intermediates located up-stream of glyceraldehyde 3-phosphate dehydrogenase (GAPDH) to increase in KRAS and BRAF mutated colorectal cancer cells, whereas metabolites down-stream of GAPDH were decreased." (PMID 27616976, 2016). "Further downstream of PFKFB3 and FBP1, glyceraldehyde 3-phosphate dehydrogenase (GAPDH) is elevated in TECs in human colorectal cancer (CRC) tissue compared to adjacent tissue ECs, contributing to the dysregulated tumor blood vessel phenotype." (PMID 39567756, 2025). "To confirm that GAPDH’s association with Rab11-exosomes is conserved in human cells, we compared small EV (sEV) preparations from human HCT116 colorectal cancer cells under glutamine-depleted versus glutamine-replete conditions." (PMID 40676215, 2025). "Literature suggests GAPDH expression to be significantly upregulated in human colorectal carcinoma tissues compared to adjacent normal tissue." (PMID 39749474, 2025). "Second, vitamin C selectively kills KRAS and BRAF mutant colorectal cancer cells by targeting glyceraldehyde 3-phosphate dehydrogenase." (PMID 35956413, 2022). "For example, GAPDH depletion affects proliferation and induces cell cycle arrest in human lung, renal and colorectal cancer cells." (PMID 35430547, 2022). "DHA, which is the oxidized product of AA, induces cell death in colorectal cancer carrying KRAS and BRAF mutation by deactivating glyceraldehyde 3-phosphate dehydrogenase." (PMID 30903981, 2019). "Other studies recently showed that vitamin C selectively killed KRAS and BRAF mutant colorectal cancer cells by targeting glyceraldehyde-3-phosphate dehydrogenase (GAPDH)." (PMID 30005692, 2018). "CRC, colorectal cancer; GAPDH, glyceraldehyde 3-phosphate dehydrogenase; PCR, polymerase chain reaction." (PMID 29523145, 2018). "The relationship between GAPDH and colorectal cancers (CRCs) is investigated in the mutant cells which are attributed to CRCs." (PMID 29511477, 2017). "We then confirmed that the relative expression level of SNHG1 in colorectal cancer tissues (n=104) compared to corresponding normal counterparts (n=104) by qRT-PCR, and normalized to GAPDH." (PMID 29340086, 2017). "Moreover, the level of GAPDH expression was up-regulated in human colorectal carcinoma tissues compared with the normal adjacent tissues, and the level of GAPDH expression was also increased in colon cancer cell lines." (PMID 36467027, 2022).
colorectal cancer (continued). "As the results of transcriptional analysis depend on genes used as normalizers, we used several internal controls, namely the most popular (GAPDH), the pair of genes previously found to be stably expressed in colorectal cancer (PPIA and RPLP0), and RN18S1, which all yielded consistent results." (PMID 34884259, 2021). "Therefore, GAPDH expression in colorectal cancer can contribute to highlight mechanisms involved in tumour progression and univocal data on patients will prompt the development of GAPDH targeted therapy in the clinical set." (PMID 34880756, 2021). "Studies on patient samples confirm the involvement of GAPDH in colorectal cancer." (PMID 34880756, 2021). "Furthermore, a recent study showed that MC-LR induced apoptosis via S-nitrosylation of GAPDH in colorectal cancer cells through a molecular mechanism of NO/GAPDH/Siah1 cascade thus supporting the role of NO in MC-LR toxicity." (PMID 33096888, 2020). "According to Bestkeeper software version 1, the most stable and suitable housekeeping genes across our colorectal cancer samples are GAPDH 2 (HGK 1) with standard deviation 0.71 and p = 0.01, PUM1 2 (HGK 2), and RPN1 (HGK 3) are equally good and have the same standard deviations 0.94 and p=0.001." (PMID 33457124, 2020). "Besides calculating fold-change expression of Notch pathway genes in adenomas and colorectal cancers relative to the adjacent normal tissues, we further calculated expression of Notch3 and Notch4 by the ΔCt method using GAPDH as reference gene in normal, adenoma, and cancer tissues." (PMID 32211044, 2020). "For example, high-dose vitamin C exhibits anticancer effect in KRAS- and BRAF-mutant colorectal cancer (CRC) cells by promoting ROS accumulation, inducing the S-glutathionylation of GAPDH at Cys152, and inhibiting glycolysis." (PMID 40227215, 2025). "In colorectal cancer cell lines (e.g., SW480, LoVo), SNHG3 was found to localize predominantly in the cytoplasm (comparable to GAPDH)." (PMID 40491847, 2025). "3-Bromopyruvate also inhibits glyceraldehyde-3-phosphate dehydrogenase (GAPDH) and a recent study indicated that 3-bromopyruvate propyl ester was a more efficient inhibitor of GAPDH compared to hexokinase in colorectal carcinoma cells." (PMID 23776707, 2013). "In colorectal cancer (CRC), KRAS mutant tumor cells increased glycolysis and glutamine utilization resulting in cell death upon inhibition of glyceraldehyde 3-phosphate dehydrogenase (GAPDH)." (PMID 36048281, 2022). "GAPDH expression levels, considering all the stages of tumour progression, were not correlated with survival in patients with colorectal cancer despite the evidence are not univocal." (PMID 34880756, 2021). "After validation with glyceraldehyde 3-phosphate dehydrogenase (GAPDH) gene expression in 3 colon cancer cell lines, a panel of 19 genes were used to analyse the single CTCs (n = 28), primary colorectal carcinoma tissues (n = 8) and colon carcinoma cells (n = 6) using real-time qPCR." (PMID 33092235, 2020). "GAPDH has been reported to be overexpressed in colorectal cancer, but has not been studied as a prognostic or predictive factor." (PMID 24324931, 2013). "For example, levels of β-catenin mRNA were found to be selectively elevated in plasma of patients with colorectal carcinomas and adenomas, but levels of glyceraldehyde-3-phosphate dehydrogenase (GAPDH) mRNA were not." (PMID 23374730, 2013). "However, in colorectal cancer tissues, GAPDH was not a good internal control gene since it showed higher transcription level than in normal mucosa, nor was β-actin." (PMID 29651323, 2018).
colon carcinoma (37 papers, 2009 to 2025). "Studies in hepatocellular carcinomas and colon cancer have shown that the β-F1-ATPase/GAPDH ratio is low in cancer cells." (PMID 41463362, 2025). "AKR1B10 was demonstrated to repress autophagy in glucose-deprived colon cancer cells by catalyzing the reduction of glyceraldehyde 3-phosphate dehydrogenase (GAPDH) thereby preventing its nuclear import as well as via inhibition of AMPK phosphorylation." (PMID 39055885, 2024). "From the known GAPDH inhibitors, vitamin C inhibits GAPDH enzyme activity and is lethal to KRAS/BRAF-mutated colon cancer cells." (PMID 36077431, 2022). "Colon cancer cell chromatin immune precipitation experiments proved the direct interaction between GAPDH and SPI transcripts, leading to the upregulation of the main regulatory factor in EMT, the zinc finger protein SNAI1 (Snail)." (PMID 34650911, 2021). "A role for GAPDH in cancer comes from the observation that CBS knockdown in colon cancer cell lines lowers GAPDH enzymatic activity." (PMID 35366284, 2021). "The crucial function of GAPDH in the regulation of tubulin, one of the most important components of the cytoskeletal network, was reported in colon cancer cell lines." (PMID 34199287, 2021). "A genome-wide microarray analysis has revealed that GAPDH is highly expressed in rapidly proliferating colon cancer cells." (PMID 34880756, 2021). "In the current study, the single-cell quantitative PCR performance was validated by gene expression of GAPDH from the colon cancer cell lines." (PMID 33092235, 2020). "Upon further analysis, low KLF4 mRNA levels were detected in most colon cancers, with the exception of Cases 3 and Case 6 (normalized to GAPDH)." (PMID 23006636, 2012). "Antisense oligonucleotides or anticancer agents targeting GAPDH could inhibit the proliferation of colon cancer cells and trigger the apoptosis of cervical cancer cells." (PMID 37671155, 2023). "Moreover, GAPDH expression was elevated in colon cancer and metastatic liver tissues, which suggested that an increased GAPDH contributed to colon cancer metastasis by providing more energy required for tumor progression." (PMID 36559193, 2022). "Livers obtained from mice inoculated with the 5.5.4 showed negligible amounts of human GAPDH compared to those inoculated with the control antibody, indicating that 5.5.4 mAb blocks the cell homing and the metastatic colonization of colon cancer cells." (PMID 33917458, 2021). "Several glycolysis genes, including glyceraldehyde-3-phosphate dehydrogenase, phosphoglycerate kinase 1 and phosphoglycerate mutase 1, have up-regulation in colon cancer tissues, therefore colon cancer cells have a higher glycolytic rate compared with normal cells." (PMID 24935220, 2014). "As it is the case for human hepatocellular carcinoma, mouse hepatoma, human colon cancer, and human lung adenocarcinoma, GAPDH represents an optimal choice of a housekeeping gene and/(or) loading control to determine the expression of hypoxia induced genes in tumors of different origin." (PMID 19144146, 2009). "Expression of GAPDH represents one of the alternatives of a housekeeping gene and can be used as a loading control in experiments with glioma cells as well as in human hepatocellular carcinoma, mouse hepatoma human colon cancer, and human lung adenocarcinoma." (PMID 19144146, 2009). "In the presented study, simultaneous incubation of zebrafish colon cancer xenografts with MM-129 and IND resulted in a significant reduction of tumor cells manifested as a strong reduction of a human GAPDH gene expression." (PMID 38201550, 2023).
colon carcinoma (continued). "The expression of GAPDH and RPL32 genes, the two well-known reference genes in the literature, was analyzed in the colon cancer cells after treatment with various concentration of glandless kernel extract." (PMID 35058516, 2022). "The other genes belong to metabolic pathways are GAPDH, INS, IGF1 which play significant role in proliferation and apoptosis in colon cancer." (PMID 30774816, 2018). "The results of the semi-quantitative PCR, which set GAPDH as an internal reference, showed that EIF3B gene was abundantly expressed in colon cancer cell SW1116." (PMID 22734884, 2012). "Glyceraldehyde 3 phosphate dehydrogenase (Gapdh) and ribosome protein L32 (Rpl32) mRNAs were not good qPCR references for the colon cancer cells." (PMID 36364387, 2022). "In this study, we have demonstrated that β-actin, GAPDH and α-tubulin are not suitable as internal reference genes in colon cancer cells treated with aspirin." (PMID 28184026, 2017). "Increased expression of GAPDH is observed in several tumors such as prostate, breast, lung and cervical carcinomas, however, there is no alteration in expression in tumors such ashepatoma, colon cancer, lung adenocarcinoma and glioblastoma." (PMID 36768815, 2023). "The large standard deviations and high expression levels of GAPDH and RPL32 mRNAs made them not good internal references for qPCR assays in the human colon cancer cells." (PMID 37705049, 2023). "We also confirmed that GAPDH and RPL32 mRNAs were not good qPCR assay references for the colon cancer cells since they were most abundant mRNAs with large variations under the cell culture conditions." (PMID 35058516, 2022). "The large standard deviations and high expression levels of GAPDH and RPL32 mRNAs suggest that they were not good internal reference genes for qPCR assays in the human colon cancer cell." (PMID 33723275, 2021). "Our results showed that GAPDH and RPL32 (60S ribosomal protein 32) mRNAs were not good qPCR assay references for the colon cancer cells since they were most abundant mRNAs with large variations under the cell culture conditions." (PMID 33723275, 2021). "GAPDH and RPL32 mRNAs were not good qPCR references for the colon cancer cells." (PMID 33723275, 2021).
diabetes (36 papers, 2009 to 2026). "With these findings, we report the pharmacological significance of isoeugenol from Ocimum tenuiflorum against diabetes-linked AD targeting GAPDH." (PMID 35458596, 2022). "Deficiencies in GAPDH activity or expression have been implicated in diseases such as neurodegenerative diseases, cardiovascular disorders, diabetes, and cancer." (PMID 33256145, 2020). "The associated region and its close neighbourhood harbours interesting candidate genes such as LETM1 and GAPDH that are important in glucose metabolism and have previously been implicated in the aetiology of diabetes mellitus." (PMID 25970163, 2015). "Given that oxidative stress and cellular apoptosis are associated with diabetes as well as impaired GAPDH activity, this 4HR-mediated increased activity of GAPDH may hold promise for mitigating diabetes-associated complications." (PMID 39596347, 2024). "Thus, the inhibition of GAPDH would be an essential step to reduce the pathogenesis of diabetes-linked AD." (PMID 35458596, 2022). "As expected, diabetes reduced Ser1177 phosphorylation of eNOS by 57% (P = 0.0257; reported to GAPDH) and 70% (P = 0.0448; reported to total eNOS) compared to normoglycemic animals but had little impact on eNOS Ser633 activation." (PMID 37636297, 2023). "We provide evidence that a glycolytic metabolite downstream of phosphofructokinase and upstream of glyceraldehyde-3-phosphate dehydrogenase (GAPDH) is instrumental in mediating the effects of diabetes and chronic hyperglycaemia on β-cell metabolism." (PMID 36376280, 2022). "Consistent with above results, diabetes caused decreases in wall thickness of the LV, fractional shortening, mitral E/A ratio, and ratio of GCH1/GAPDH and increases in LV internal diameters and IVRT 12 weeks after administration of STZ." (PMID 27295516, 2016). "As diabetes can modulate heart glyceraldehyde 3-phosphate dehydrogenase (GAPDH) content expression, data can be normalized to cyclophilin expression." (PMID 24502618, 2014). "2SC has been described in aging and diabetes, and its functional consequences have been reported for GAPDH and adiponectin in addition to the KEAP1/NRF2 pathway." (PMID 23499446, 2013). "Oxidative stress is elevated in diabetes, GAPDH is inactivated under conditions of mild oxidative stress, and fisetin has dual antioxidant functions by maintaining intracellular GSH levels and acting as a direct antioxidant." (PMID 21738623, 2011). "The downregulation of mitochondrial respiratory capacity in diabetes may result from a variety of factors, such as increased production of ROS and GAPDH inhibition." (PMID 39396937, 2024). "In addition, we show diabetes dramatically inhibits the activity of GAPDH and pyruvate dehydrogenase (PDH), impairing both glycolytic metabolism and pyruvate entry into the TCA cycle." (PMID 36376280, 2022). "AHR transcript (relative to that of GAPDH) turned out to be the only independent risk factor of increased CRP levels [β Coefficient: 55.04(18.65–91.43), P = 0.005**], even after adjusting sex, age, disease status (diabetes duration, and medications)." (PMID 32849564, 2020). "AHR transcript (relative to that of GAPDH) turned out to be an independent risk factor of increased CRP levels [β Coefficient: 9.25(0.46–18.03), P = 0.040*], even after adjusting sex, age, disease status (diabetes duration and medications)." (PMID 32849564, 2020). "However, increased ratio of iNOS/GAPDH by diabetes was significantly reduced by GCH1 overexpression." (PMID 27295516, 2016). "Hence, it is conceivable that the oxidant-induced relocation of GAPDH is common to diabetes, cancer, and some forms of neurodegeneration." (PMID 22028962, 2012). "Nuclear translocation of glyceraldehyde-3-phosphate dehydrogenase (GAPDH) is thought to be a critical step in the diabetes-induced apoptosis of retinal Müller cells, and this mechanism is reported to play a significant role in the development and progression of diabetic retinopathy." (PMID 21151599, 2010).